TFE3 (transcription factor binding to IGHM enhancer 3)
Diseases named in the same sentence as TFE3 in open-access papers (continued):
Sharing a sentence is not in itself a finding about the gene and the disease.
renal cell carcinoma (continued). "Nevertheless, it is widely accepted that both TFE3-rearranged renal cell carcinoma and TFEB-rearranged renal cell carcinoma may show a broad range of morphology, resulting in a challenging differential diagnosis." (PMID 34069976, 2021). "Transcription factor binding to IGHM enhancer 3 (TFE3) is related to renal cell carcinoma." (PMID 34409913, 2021). "TFE3 is also involved in gene fusions in renal cell carcinoma and alveolar soft part sarcoma." (PMID 33913810, 2021). "Conversely, cathepsin K is unevenly observed in TFE3-rearranged renal cell carcinomas." (PMID 34069976, 2021). "As the target DNA sequences of MiTF overlap with those of TFE3 and TFEB, it has been hypothesized that the overexpressed TFE3 fusion proteins or native TFEB in these renal cell carcinomas may have the same effect on the promoter of cathepsin K." (PMID 34069976, 2021). "At the gene level, renal cell carcinoma (RCC) is associated with TFE3 (transcription factor E3)‐NONO fusion." (PMID 32168434, 2020). "TFE3 acts as an oncogene which is commonly rearranged in many tumour types, such as translocation of Xp11.2 leading to renal cell carcinoma, alveolar soft tissue sarcoma (ASPS), a subset of perivascular epithelioid cell tumours (PEComas), and partial epithelioid hemangiosarcoma." (PMID 32566457, 2020). "The function of chimeric TFE3 fusion proteins can also vary, which may explain the different histological features observed in this tumor entity of renal cell carcinoma." (PMID 31382581, 2019). "Xp11 translocation renal cell carcinoma (RCC), a member of the microphthalmia-associated transcription factor (MiTF) family, is a rare renal tumor characterized by different translocations involving the TFE3 gene." (PMID 31828108, 2019). "Teleologically, this anomaly may contribute to tumor development analogous to what has been suggested for CLTC fusions with ALK in inflammatory myofibroblastic tumors and anaplastic large-cell lymphomas, and with TFE3 in renal cell carcinomas." (PMID 21152103, 2010). "In this regard, TFE3 is involved in chromosomal translocations recurrent in renal cell carcinoma." (PMID 17705868, 2007). "TFE3-rearranged renal cell carcinoma (TFE3-RCC) is a rare molecular subtype of renal cell carcinoma (RCC), characterized by Xp11.2 translocations involving the TFE3 gene." (PMID 42220779, 2026). "In addition to TFE3, cathepsin K also shows consistent diffuse positivity in ASPS, which is helpful for differential diagnosis against other tumors such as renal cell carcinoma, ASPCR1-TFE3 translocation renal cell carcinoma, adrenal cortex carcinoma, and paraganglioma." (PMID 41446840, 2025). "According to previous studies, TFE3-RCC has strong invasion, rapid progression, and poor prognosis compared to common types of renal cell carcinoma." (PMID 38261736, 2024). "The described morphologic findings, in relation to the patient’s young age, raised the suspicion for translocation-type renal cell carcinoma, with TFE3-rearranged RCC being the most prevalent pediatric RCC subtype." (PMID 39206137, 2024). "TFE3-rearranged Renal Cell Carcinoma (TFE3-RCC) is a distinct subset of RCC, defined in the 2022 WHO classification, characterized by Xp11.2 rearrangements that result in TFE3 gene fusions with various partner genes." (PMID 39727945, 2024). "However, the first description of TFE3-rearranged renal cell carcinoma is commonly considered in 2001 by Argani who reported eight renal tumors arising in children characterized by a t(X;17)(p11.2;q25) translocation, which fuses the ASPL/ASPSCR1 and TFE3 genes." (PMID 39410016, 2024).
renal cell carcinoma (continued). "Histologically, TFE3-rearranged RCC can mimic other renal cell neoplasms including clear cell renal cell carcinoma, papillary renal cell carcinoma, and clear cell papillary renal cell tumor." (PMID 39502747, 2024). "The TFE3-RCC incidence in adults is very low, accounting for approximately 0.9%–4% of renal cell carcinoma cases." (PMID 38261736, 2024). "Meanwhile, many studies have reported that the initial diagnosis of TFE3‐rearranged RCC was misdiagnosed as clear cell renal cell carcinoma or renal papillary cell carcinoma." (PMID 38477529, 2024). "TFE3 Xp11.2 translocation renal cell carcinoma (TFE3-RCC) has a more aggressive growth pattern than other RCC subtypes, but TFE3-RCC is very difficult to diagnose using standard light microscopy." (PMID 38001875, 2023). "MiT family translocation renal cell carcinoma (tRCC) is a sporadic RCC characterized by fusion genes involving the MiT/TFE family genes, MITF, TFEB, and TFE3 and defined as an MiT family translocation RCC in the 2016 WHO classification." (PMID 36672892, 2023). "TFE3-rearranged renal cell carcinoma may also resemble clear cell papillary renal cell tumor." (PMID 35980471, 2022). "Additionally, TFE3 gene fusion has been described, as in TFE3-rearranged renal cell carcinoma." (PMID 34069976, 2021). "Based on the histological appearance, RCC can be divided into several subsets including papillary renal cell carcinoma which is characterized by the expression of TFE3 fusion proteins." (PMID 32168434, 2020). "The tight connection of TFEB and TFE3 with RCC has been reported, especially in translocation renal cell carcinoma." (PMID 33145941, 2020). "MiT/TFE family translocation renal cell carcinoma (tRCC) comprises Xp11 tRCC and t(6:11)RCC, which were characterized by the rearrangement of the MiT transcription factors TFE3 and TFEB, respectively." (PMID 29903018, 2018). "Microphthalmia Transcription Factor (MiTF) family translocation renal cell carcinoma (tRCC) is a subtype of RCC characterized by chromosomal translocations involving TFE3 and TFEB transcription factor genes." (PMID 30591082, 2018). "Microphthalmia Transcription Factor (MITF)family translocation renal cell carcinoma (tRCC) is a rare RCC subtype harboring TFE3/TFEB translocations." (PMID 30591082, 2018). "Interestingly, fusions of CLTC with the anaplastic lymphoma kinase (ALK) have been encountered in inflammatory myofibroblastic tumors and anaplastic large-cell lymphomas, whereas fusions with the transcription factor TFE3 have been encountered in renal cell carcinomas (RCC)." (PMID 21152103, 2010). "Renal cell carcinoma (RCC) is uncommon in the pediatric population, and the TFE3-rearranged RCC (tRCC) subtype is characterized by translocation at Xp11.2." (PMID 40718162, 2025). "Postoperative pathology confirmed the presence of Mit family (TFE3/Xp11) translocation renal cell carcinoma, immunohistochemistry is shown in, confirmed by parallel FISH assay showing TFE3-related translocation." (PMID 40177240, 2025). "TFE3 rearrangements are characteristic of alveolar soft part sarcomas (ASPS), Xp11.2 translocation renal cell carcinomas (Xp11-RCC), besides EHE with TFE3 rearrangement." (PMID 39917171, 2025). "Additionally, in NONO-TFE3 translocation renal cell carcinoma (NONO-TFE3 tRCC), a subtype of RCC associated with Xp11.2 translocation/TFE3 gene fusions RCC (Xp11.2 tRCCs), YTHDF2 played a tumor-suppressive role by suppressing poly(ADP-ribose) polymerase 1 (PARP1) expression." (PMID 38503745, 2024). "As per the recent WHO classification, TFE3 rearranged RCC and TFEB altered RCC are now considered as two separate molecularly defined renal cell carcinomas." (PMID 38265103, 2024). "Although the ASPSCR1::TFE3 fusion in sarcomas appears highly specific and sensitive for ASPS, the same gene fusion is also found in a small subset of TFE3-rearranged renal cell carcinomas that affect young patients and have a morphology similar to ASPS." (PMID 36983010, 2023).
renal cell carcinoma (continued). "The pathological features of twenty-seven TFE3-rearranged renal cell carcinomas and ten TFEB-rearranged renal cell carcinomas have already been reported." (PMID 35980471, 2022). "Despite initially considered rare tumors, TFE3 and TFEB-rearranged renal cell carcinoma represent 1–4% of renal cell carcinomas diagnosed among adults." (PMID 35980471, 2022). "When TFE3 and TFEB-rearranged renal cell carcinomas exhibit extensive eosinophilic features, they can mimic oncocytoma and the eosinophilic variant of chromophobe renal cell carcinoma." (PMID 35980471, 2022). "Of course, staining for CK7 favors papillary renal cell carcinoma, confirming its usefulness in distinguishing papillary renal cell carcinoma from TFE3 and TFEB-rearranged renal cell carcinomas." (PMID 35980471, 2022). "In general, TFE3 and TFEB-rearranged renal cell carcinomas ought to be considered in the differential diagnosis, especially in young patients, every time pathologists have to deal with a renal tumor showing unusual microscopic findings." (PMID 35980471, 2022). "TFE3 gene translocations, and less frequently TFEB, are detected in renal cell carcinoma, alveolar soft part sarcoma, and perivascular epithelioid cell neoplasm." (PMID 33981707, 2021). "NONO-TFE3 translocation renal cell carcinoma (NONO-TFE3 tRCC) is one subtype of RCCs associated with Xp11.2 translocation/TFE3 gene fusions RCC (Xp11.2 tRCCs)." (PMID 33741027, 2021). "In the nineties, among Xp11 renal cell carcinoma, ASPL, PRCC, and SFPQ (PSF) were the first genes recognized as partners in TFE3 rearrangement." (PMID 31382581, 2019). "It has long been documented that multiple translocation events, resulting in five described TFE3 gene-fusion products and one TFEB gene fusion product, result in renal cell carcinoma (RCC)." (PMID 30520728, 2018). "The tight connection of TFEB and TFE3 with clear cell renal cell carcinoma (RCC) has been reported." (PMID 29903018, 2018). "In the specific context of renal cell carcinoma, MED15 has been identified as a fusion partner of TFE3 in a rare subtype, suggesting that aberrant activation of the TFE3-MED15 fusion protein may contribute to tumorigenesis." (PMID 39947475, 2025). "The t(X,17) chromosomal translocation, generating the ASPSCR1::TFE3 fusion oncoprotein, is the singular genetic driver of alveolar soft part sarcoma (ASPS) and some Xp11-rearranged renal cell carcinomas (RCCs), frustrating efforts to identify therapeutic targets for these rare cancers." (PMID 38326311, 2024). "Additionally, melanogenesis markers such as Melan-A and HMB45 are found in TFE3-rearranged renal cell carcinoma, although less frequently compared to their occurrence in TFEB-rearranged renal cell carcinoma." (PMID 39410016, 2024). "Although over the past 30 years, numerous fusion partners have been identified in TFE3-rearranged renal cell carcinoma and PEComa, ASPL/ASPSCR1, PRCC, SFPQ, NONO, and MED15 remain the most frequent in both groups of neoplasms." (PMID 39410016, 2024). "If IHC is not used at the time of diagnosis, a large proportion of TFE3-rearranged renal cell carcinomas are likely to be misdiagnosed as ccRCC." (PMID 37367052, 2023). "NONO-TFE3 rearranged renal cell carcinoma (NONO-TFE3 rRCC) is one of a subtype of TFE3 rRCCs with high malignancy and poor prognosis." (PMID 37770905, 2023). "Previous studies identified numerous ASPSCR1::TFE3 targets that are involved in growth signaling, lysosomal functions, autophagy, and angiogenesis in both ASPS and fusion-positive renal cell carcinoma, with the latter exhibiting a vascular structure similar to that of ASPS21,22,24,25,36." (PMID 37029109, 2023). "The forthcoming Word Health Organization (WHO) includes TFE3-rearranged renal cell carcinoma and TFEB-rearranged renal cell carcinoma as separate entities differentiating from the previous one in which the term “MiT family translocation renal cell carcinoma” encompassed both tumor types." (PMID 35980471, 2022).
renal cell carcinoma (continued). "Recently, the expression of TRIM63 by RNA in situ hybridization (RNA-ISH) assay has been proposed as another diagnostic marker for TFE3 and TFEB-rearranged renal cell carcinoma even if an external validation has not been performed so far." (PMID 35980471, 2022). "Xp11.2 translocation renal cell carcinoma (Xp11.2 translocation RCC), first classified by WHO in 2004, is characterized by different tanslocations involving chromosome Xp11.2 and consequently results in gene fusions of the transcription factor E3 gene (TFE3)." (PMID 35850864, 2022). "CK7 is usually negative either in TFE3 or TFEB-rearranged renal cell carcinoma whereas it is an important positive reliable marker in papillary renal cell carcinoma." (PMID 35980471, 2022). "CK7 is negative in TFE3/TFEB-rearranged renal cell carcinoma and positive in papillary renal cell carcinoma, being therefore useful in this setting." (PMID 35980471, 2022). "Finally, the study highlighted the importance, also from an immunohistochemical point of view, to maintain TFE3 and TFEB-rearranged renal cell carcinoma as distinct entities, as recommended by the forthcoming WHO classification of renal tumors." (PMID 35980471, 2022). "CA9 is usually negative either in TFE3 or TFEB-rearranged renal cell carcinoma whereas it is an important positive reliable marker in clear cell renal cell carcinoma." (PMID 35980471, 2022). "On the other hand, cathepsin K is positive in TFEB-rearranged renal cell carcinoma and half of TFE3-rearranged renal cell carcinoma while it is negative in papillary renal cell carcinoma." (PMID 35980471, 2022). "Cathepsin K is positive in TFEB-rearranged renal cell carcinoma and half of TFE3-rearranged renal cell carcinoma while it is negative in chromophobe renal cell carcinoma." (PMID 35980471, 2022). "On the other hand, cathepsin K is positive in TFEB-rearranged renal cell carcinoma and half of TFE3-rearranged renal cell carcinoma while it is negative in clear cell renal cell carcinoma." (PMID 35980471, 2022). "We performed an immunohistochemical panel comparing 27 TFE3-rearranged and 10 TFEB-rearranged renal cell carcinomas to the most common renal cell tumors (150 clear cell, 100 papillary, 50 chromophobe renal cell carcinomas, 18 clear cell papillary renal cell tumors, and 50 oncocytomas)." (PMID 35980471, 2022). "While AMACR is not useful in the differential diagnosis with TFE3-rearranged renal cell carcinomas, being positive in both tumors, such marker is usually under-expressed in TFEB-rearranged renal cell carcinomas." (PMID 35980471, 2022). "While the expression is lower for TFE3-rearranged renal cell carcinomas (41%, 33%, and 29% respectively with a 5%, a 10%, and 20% threshold), most of TFEB-rearranged renal cell carcinomas labeled positive for CK8-18 (100%, 80%, and 60% respectively with 5%, 10%, and 20% threshold)." (PMID 35980471, 2022). "Cathepsin K is positive in TFEB-rearranged renal cell carcinoma and half of TFE3-rearranged renal cell carcinoma while it is negative in clear cell papillary renal cell tumor." (PMID 35980471, 2022). "Thus, chromosomal translocation of TFE3 and TFEB genes are detected in renal cell carcinoma, alveolar soft part sarcoma, and perivascular epithelioid cell neoplasm." (PMID 33981707, 2021). "Indeed, cathepsin K is expressed in roughly half of TFE3-rearranged renal cell carcinomas, and is observed in virtually all TFEB-rearranged renal cell carcinomas." (PMID 34069976, 2021). "Xp11.2 translocation renal cell carcinoma (Xp11.2 translocation RCC) is a rare subtype of renal cell carcinoma (RCC), characterized by several different chromosomal translocations involving Xp11.2 and the formation of TFE3 fusion genes, followed by overexpression of TFE3 protein." (PMID 33267784, 2020).
renal cell carcinoma (continued). "The three most common Xp11 translocation renal cell carcinomas are those bearing the t(X;1) (p11.2;q21) which fuses the PRCC and TFE3 genes, the t(X;17) (p11.2;q25) which fuses the ASPL and TFE3 genes, and the t(X;1) (p11.2;p34) which fuses the SFPQ (PSF) and TFE3 genes." (PMID 31382581, 2019). "While not as widely associated with all cancers, TFE3 and TFEB gene fusions are detected in subsets of renal cell carcinomas (RCC), indicating roles for these transcription factors in oncogenesis." (PMID 30520728, 2018). "We evaluated the frequency of translocation renal cell carcinoma (RCC) by reverse transcription polymerase chain reaction (RT-PCR) and how well the TFE3 immunoreactivity is concordant with TFE3 gene translocation status proved by fluorescence in situ hybridization (FISH) assay and RT-PCR." (PMID 28415646, 2017). "Xp11.2 or TFE3 translocation renal cell carcinomas (RCC) and alveolar soft part sarcoma (ASPS) are characterized by chromosome translocations involving the Xp11.2 breakpoint resulting in transcription factor TFE3 gene fusions." (PMID 26415891, 2015). "However, this hypothesis remains debated, as renal cell carcinomas with the Xp11.2 translocation can also harbor other TFE3 fusion genes, like PRCC-TFE3." (PMID 40176092, 2025). "Notably, cathepsin K is expressed in approximately 60% of TFE3-rearranged renal cell carcinomas and is consistently negative in other common renal cell neoplasms." (PMID 39410016, 2024). "However, those melanotic Xp11 neoplasms arising in the kidney clustered with TFE3-rearranged renal cell carcinoma rather than with alveolar soft part sarcoma." (PMID 39410016, 2024). "Furthermore, renal cell carcinoma cells in vitro with TFE3 fusions are capable of growth independent of mTOR signaling." (PMID 37041531, 2023). "For instance, staining for CD10 which is usually observed in TFE3-rearranged renal cell carcinoma and under-expressed in TFEB-rearranged renal cell carcinoma seems significant in the differential diagnosis of MiT family translocation renal cell carcinoma and clear cell renal cell carcinoma." (PMID 35980471, 2022). "Namely, whereas CA9 immunolabeling was found in 6 of 25 (24%) TFE3-rearranged renal cell carcinomas with a 5% threshold, in 2 of them (8%) and none of them (0%), respectively, referring to a 10% and 20% cutoff, all the TFEB-rearranged renal cell carcinomas were negative for such marker." (PMID 35980471, 2022). "CD10 is not useful in the differential diagnosis between clear cell papillary renal cell tumor and TFEB-rearranged renal cell carcinoma since both tumors are typically negative for this marker, but it helps distinguish from TFE3-rearranged renal cell carcinoma, usually positive." (PMID 35980471, 2022). "The scope of this review will focus only on the more recently described entities and not the common ones, such as clear cell renal cell carcinoma (RCC), papillary RCC, chromophobe RCC (classic), as well as TFE3‐rearranged RCC and TFEB‐altered RCC, all of which commonly exhibit eosinophilic features." (PMID 41384711, 2026). "At present, most of the studies on TFE3 and cancer focus on Xp11.2 translocation renal cell carcinoma (tRCC) but not ccRCC, a special type of RCC characterized by gene fusions involving TFE3 or TFEB." (PMID 33637706, 2021). "TFE3 rearrangements are not specific to ASPS but have also been identified in a subset of PEComa and a Mit Translocation renal cell carcinoma, both of which are morphological mimickers of ASPS." (PMID 37218666, 2024). "In these challenging cases, PAX8 (positive in TFE3-rearranged renal cell carcinoma and negative in pure epithelioid PEComa) and CD68 (PG-M1) (negative in TFE3-rearranged renal cell carcinoma and positive in pure epithelioid PEComa) are useful markers to reach the proper diagnosis." (PMID 39410016, 2024).